PRLR (prolactin receptor)
Diseases named in the same sentence as PRLR in open-access papers (continued):
Sharing a sentence is not in itself a finding about the gene and the disease.
tumor (continued). "Additionally, PRLR and SOCS2 could promote the expression of phosphoinositide-3 kinase (PI3K) and programmed death ligand 1 (PD-L1), which can protect tumor cells from T cell-mediated immune surveillance, and immune checkpoint blockade (ICB) therapies." (PMID 35739271, 2022). "Since the PRLR/PRL axis has been implicated in other tissues, including reproductive tissues and prostate, h16f-MMAE and ABBV-176 conjugates were evaluated for their ability to inhibit the growth of non-breast-derived tumor cell lines." (PMID 34107902, 2021). "Inflammation in the tumor microenvironment and production of inflammatory cytokines such as TNF-α, IL-1β, and IFNγ (that could also be induced by HCMV) may lead to further induction of PRLR." (PMID 32121009, 2020). "Importantly, all mice within the MDA-MB-231/PRLR treated group failed to develop any detectable tumors throughout the period examined suggesting that PRL abrogates tumor formation in vivo." (PMID 27480353, 2016). "In both cases, co-localization was observed in the tumour tissue for anti-PRLr and the lysosomal marker in the “ring-like” structures, but not for the Golgi marker (data not shown), suggesting that they originate from PRLr localized to enlarged lysosomes." (PMID 22606260, 2012). "Importantly, in vivo studies confirm that oral administration of 4SC-202 significantly inhibits tumor growth and reduces PRLR pathway activity within the tumor tissue, with no observed significant hepatotoxicity or organ pathological damage, highlighting its excellent in vivo safety profile." (PMID 40657246, 2025). "RNA expression of GH, GHR, IGF1, IGF1R, and PRLR is also detected using qPCR, and IGF1 production in tumor cells is markedly lower in mouse tumor cells but not in human tumor cells." (PMID 39000545, 2024). "Similar to the orthotopic location, we now find that SSM2 tumor cells growing in bones of OVX mice show phosphorylation of JAK2 and STAT3, suggesting activation of the PrlR signaling pathway in the absence of estrogen." (PMID 27391074, 2016). "However, not all PRLR-expressing cells within the tumor tissues were positive for HCMV proteins, which indicates both a direct and potentially also indirect effect of HCMV on PRLR expression." (PMID 32121009, 2020). "Additionally, as with PRL and PRLR, the base RNA levels of IGF1 were 3-fold lower than GH levels and the modulated-GH-action induced changes in IGF axis apparently had no observable variation on intracellular signaling or tumor phenotypes." (PMID 28223541, 2017).
cancer (70 papers, 2003 to 2025). A tumor composed of atypical neoplastic, often pleomorphic cells that invade other tissues. "Little attention has, however, been given to the role of membrane composition for PRLR signaling, despite it being placed in the plasma membrane where PI levels are highly dynamic and spatially variable and being linked to cancer with lipid deregulation." (PMID 37232489, 2023). "Due to their cell proliferative property, PRL has been implicated in the initiation and progression of cancers; antagonizing PRLR in certain tumors has therefore shown anti-proliferative effects on their cells." (PMID 35406699, 2022). "Several publications suggest that activation of the PRL/PRLR signaling pathways is linked to cancer via activation of JAK/STAT, PI3K, AKT and MAPK pathways." (PMID 34358244, 2021). "Several publications suggest that activation of the PRL/PRLR signaling pathways is linked to cancer via activation of PI3K, AKT, and MAPK pathways, which are important in tumorigenesis." (PMID 32121009, 2020). "They includes known cancer-associated pathways ‘phosphatidylinositol phosphate metabolism’, ‘prolactin receptor signalling’ and ‘platelet-derived growth factor receptor (PDGFR)-beta signalling’." (PMID 28592290, 2017). "The abnormal induction of PRL/PRLR has been associated with the development and progression of various types of cancers such as breast, prostate, colorectal, larynx, and hepatocellular." (PMID 26346346, 2015). "To date, several reports associate the expression of the PRL/PRLR with the development and progression of cancers such as breast, prostate, colorectal, gynecological, laryngeal, and hepatocellular." (PMID 24148306, 2013). "The altered expression of prolactin (PRL) and its receptor (PRLR) has been implicated in breast and other types of cancer." (PMID 24148306, 2013). "Moreover, they found that cancers with a high ratio of transcripts for the “intermediate” to the “long” PRLR isoform were associated with greater likelihood of distant metastases in the TCGA database." (PMID 35784527, 2022). "However, little is known about the short isoform (PRLR-SF), particularly in cancer development and metabolic reprogramming, a core hallmark of cancer." (PMID 33664869, 2021). "Loss of PRLR in HER2+ cancer cells enhanced tumorigenesis, metastasis, and resistance to therapy." (PMID 34572912, 2021). "Early studies with the PRLR antagonist hPRL-G129R – a variant of normal human prolactin with a single amino acid substitution mutation – revealed its capacity to inhibit the prolactin-induced oncogenic signaling responsible for cancer cell proliferation." (PMID 33335078, 2020). "Before implementing molecular imaging of PRLR-positive cancer cells in clinical practice, additional research is necessary to optimize the human placental lactogen conjugate." (PMID 39928792, 2025). "PRLR regulation by miR-181b in cancers needs to be elucidated since both play important roles in cellular metabolism." (PMID 40149537, 2025). "High PRLR levels (genetically predicted or measured via gene expression) indicate the priming of cancer cells towards radioresistance, but further explorations are required." (PMID 40723262, 2025). "While the normal physiological role of GH's lactogenic activity is disputed, hGH has been shown to stimulate the growth of PRLR‐positive cancers such as breast, prostate, and colon." (PMID 40524488, 2025). "Although the activation of PRLR pathway has been identified as a cancer promoter, targeting PRL-PRLR axis alone achieves limited effects in clinical trials." (PMID 38898487, 2024). "The PRLR is expressed on the surfaces of some HER2-positive cancer cells and can enhance the proliferation and survival of these cells." (PMID 37298631, 2023). "Prolactin (PRL)-dependent signaling occurs as the result of ligand-induced dimerization of the prolactin receptor, their interaction can modulate the endocrine and autocrine effects of prolactin in normal tissue and cancer." (PMID 37490712, 2023).
cancer (continued). "In this review, we will summarize the recent advances in the biology of this receptor in cancer and give an account of PRLR antagonist development for the treatment of cancer." (PMID 36714582, 2022). "The efficacy of these preclinical studies demonstrates the validity of targeting PRLR while also establishing the critical role of PRL : PRLR signaling in human cancers." (PMID 36714582, 2022). "Due to the strong evidence supporting the critical role of PRL and PRLR in human cancers, various approaches have attempted to modulate activity both by suppressing downstream signaling as well as by developing PRLR antagonists." (PMID 36714582, 2022). "Due to the extensive expression of PRL and PRLR in various tissues, and the efficacy of preclinical inhibitory strategies, it is clear that the PRL : PRLR signaling axis is a critical pathway in human biology and cancers." (PMID 36714582, 2022). "PRLR KD resulted in significant inhibition of proliferation, colony formation, migration, and spheroid formation, suggesting that PRLR regulated multiple hallmarks of cancer progression." (PMID 36714582, 2022). "We have summarized below several studies focused on developing small molecule inhibitors for targeting PRLR, which have largely been conducted in the context of cancer." (PMID 36714582, 2022). "Taken together, these studies demonstrate antagonistic activity of G129R-hPRL, despite previous confounding studies, and show the feasibility of inhibiting PRLR signaling to suppress cancer growth." (PMID 36714582, 2022). "We compared the mRNA expression of PRLR in cancer tissues and paracancerous tissues of various malignant tumors." (PMID 34539753, 2021). "The prolactin receptor (PRLR) was shown to play an intimate role in a mouse model of cancer-fibroblast interactions by mediating micrometastases via COX-2; COX-2 inhibition was shown to reduce tumorigenesis." (PMID 34667228, 2021). "Serum PRL levels are considerably elevated in patients with EC compared to levels in cancer-free patients, as well as PRLR, and PRL mRNA are overexpressed in endometrial tumors." (PMID 34745013, 2021). "The study found that the CAF proportion was significantly negatively correlated with PRLR in various malignant tumors, including ccRCC (rho =−0.11,p < 0.001)." (PMID 34539753, 2021). "Findings of increased PRLR levels in tumors combined with a frequently observed elevation of serum PRL in cancer patients formed the basis for a clinical trial to suppress serum PRL with dopamine receptor agonists." (PMID 32121009, 2020). "Both in vitro and in vivo experiments showed PRLR-DbsAb had a potential therapy of cancer treatment potential therapy for cancer." (PMID 32398042, 2020). "We and others have previously found evidence to suggest that the Prl/PrlR axis can act to promote cancer development and would thus be a suitable target for development of cancer drugs." (PMID 31063493, 2019). "A prospective study already in progress will show if female dogs affected by malignant tumors in fact have increased PRL levels in addition to decreased tumorous PRLR expression." (PMID 22647582, 2012). "Given the negative findings between circulating hPRL and prognosis in SCCHNs, we decided to study the expression of PRLR within SCCHN cancer tissue." (PMID 21505459, 2011). "Furthermore, 20K hGH‐V‐treated prolactin receptor‐positive cancer cells exhibited significantly less growth compared to hGH treatment." (PMID 40524488, 2025). "Deregulation of PRLR/PRL signaling is linked to other diseases and, although still debated, suggested to be implicated in the development and progression of prostate and breast cancers." (PMID 37232489, 2023). "Using a cohort of 298 urothelial cancer patient treated with the PD-L1 blockade cancer immunotherapy agent atezolizumab, we found that PRLR showed significant gene expression differences between 68 responders and 230 non-responders (fold change = 1.5, moderated t-test P = 0.049)." (PMID 35739271, 2022).
cancer (continued). "The secretion of prolactin remarkably increases during pregnancy and lactation 46, implying that PRL/PRLR might contribute to the correlation between cancer development and pregnancy/lactation." (PMID 33664869, 2021). "Alternatively, increased PRLR levels may form a base for the development of PRLR antagonist or PRLR antagonist-drug conjugate to increase selective uptake of anti-cancer drugs." (PMID 34358244, 2021). "The increase in PRLR-SF during pregnancy and lactation might help reduce the risk of PDAC and other cancers by dual functions: trigging the Hippo-PPP pathway and diminishing PRLR-LF effects." (PMID 33664869, 2021). "Increased PRLR levels in tumors may therefore be a sign of increased PRL stimulated cancer cell growth." (PMID 34358244, 2021). "Alternatively, increased PRLR levels may form the bases for the creation of drugs conjugated to PRLR antagonists to increase selective uptake of anti-cancer drugs." (PMID 34358244, 2021). "Besides, it has been observed that some infections can regulate the PRL/PRLR axis, thus favoring cancer progression." (PMID 34745013, 2021). "PRL and its receptor (PRLR) activate a series of effects such as survival, cellular proliferation, migration, invasion, metastasis, and resistance to treatment, being highly relevant in developing certain types of cancer." (PMID 34745013, 2021). "Prolactin (PRL) and its receptor (PRLR) are also important in CC; previous reports of our group of research have shown that PRLR expression in cervical tissue is increased as the disease advances towards cancer." (PMID 31507337, 2019). "Besides, the long isoform of PRLR was only expressed in CC, which suggests a differential signaling of this hormone-receptor axis between pre-malignant and cancer stages." (PMID 31507337, 2019). "Only PRLR in malignant tumors seems to be influenced by circulating PRL levels." (PMID 26370564, 2015). "PRLR staining was heterogeneous on the cell surface and in the cytoplasm of all cancer cells lines." (PMID 24148306, 2013). "Growth of PRLR-positive cancer cells increased in response to hPRL treatment." (PMID 21505459, 2011). "Furthermore, our data suggest that human hPRL is a growth factor for SCCHNs and that it promotes the proliferation of PRLR-positive cancer cells." (PMID 21505459, 2011). "This approach is promising as PRLR inhibition could serve as a novel strategy for the treatment of cancer." (PMID 21505459, 2011). "Thus, given the widespread expression of PRLR in cancer, its interaction with several known signal transduction pathways and the availability of PRLR antagonists, PRLR represents an attractive drug target." (PMID 21505459, 2011). "Long and short isoforms of the prolactin receptor have been described in the hippocampus; however, the long isoform is more highly expressed in the hippocampus and in certain types of cancer, which could be related to cell proliferation." (PMID 40507839, 2025). "Finally, some infections can also regulate the PRL/PRLR axis, thus regulating cancer promotion." (PMID 34745013, 2021). "Collectively, this study defines PRLR as a driver of precise luminal and epithelial differentiation limiting cellular plasticity, stemness, and tumorigenesis and emphasizing the function of pro/forward-differentiation pathways as a foundation for the discovery of anti-cancer therapeutic targets." (PMID 33446633, 2021). "Together with the suppressive role of PRLR-SF on PDAC cell growth, these results suggest that alteration of the PRLR-SF: PRLR-LF ratio induced by pregnancy and lactation might contribute to a reduced cancer risk in women." (PMID 33664869, 2021). "We showed that loss of PRLR expression in HR+ and HER2-E cells caused dedifferentiation in their molecular phenotype and increased their survival, migratory, and invasive properties, all of which are indicators of the acquisition of a cancer stem-like phenotype." (PMID 33446633, 2021).
cancer (continued). "Although PRLR and ERBB receptors are critical regulators of normal developmental processes, such as growth and morphogenesis of mammary glands, it has become increasingly evident that their dysregulation, because of overexpression, and/or mutations, leads to the development of cancer." (PMID 34572912, 2021). "Increased PRLR levels in tumors may therefore stimulate cancer cell growth via PRL." (PMID 32121009, 2020). "We assessed the effects of an Akt1/2 inhibitor and the mTOR inhibitor, everolimus, which is a Food and Drug Administration-licensed drug for use in a number of cancers and acts on the Akt pathway, on pAkt and proliferation responses in cells expressing the WT PRLR and mutant Asn492Ile PRLR." (PMID 30445560, 2019). "A plausible explanation for the fact that PRLR expression was highest in canine normal mammary tissue and lowest in malignant tumors is that PRLR expression may be a differentiation marker of mammary epithelial cells and that loss of this marker may be a characteristic of dedifferentiation." (PMID 22647582, 2012). "Although it has been extensively described that ev21 causes the negative side effects of the K allele, the findings of this study might also indicate involvement of PRLR. prolactin and its receptor are involved in the growth of different forms of cancer, egg production, and in the immune system." (PMID 18713476, 2008). "ABBV-176, a PRLR targeting antibody-drug conjugate (ADC), significantly suppresses cancer progression." (PMID 38898487, 2024). "For example, as with the PRLR mediated activation of STAT3, targeting this upstream regulator of the pathway provides a promising outlook on treating patients with various cancers including PDAC." (PMID 38464736, 2024). "High expression of PRLR and circulating PRL can drive the expression of genes involved in proliferation, migration, and invasion of cancer cells." (PMID 36714582, 2022). "In fact, penfluridol was shown to target the JAK2 binding site in PRLR, thereby suppressing JAK2–STAT3 and ERK/AKT signaling, which are key players in cancer cell proliferation, migration, apoptosis and in conferring stem-cell features." (PMID 34439102, 2021). "The long form of the human Prolactin Receptor (PRLR) of 622 amino acids with extended cytoplasmic domain present in the cell membrane of normal and cancer cells mediates all the known diverse functions of prolactin (PRL)." (PMID 27564112, 2016). "In these six cancer-related pathways, four genes (IL8, PRLR, EFNA1, and CHP2) were uniquely regulated by one specific miRNA each (hsa-miR-338-5p_IL8, hsa-miR-338-5p_PRLR, hsa-miR-760_EFNA1, hsa-miR-450b-5p_CHP2)." (PMID 26259570, 2015). "Expression of many ERα target genes, including GREB1 (gene regulated in breast cancer 1), PGR (the progesterone receptor gene) and PRLR (the prolactin receptor gene), was induced by oestradiol and blocked by fulvestrant, but only in cells transduced with ERα." (PMID 17573968, 2007). "An ADC targeting PRLR, termed ABBV-176, could deliver pyrrolobenzodiazepine into cancer cells and significantly inhibits BC cells preclinically." (PMID 38898487, 2024). "Further, three up-regulated genes, PRLR, NOX1, and PGF, also contributed to several hallmarks of cancer, mainly including insensitivity to antigrowth signals, self-sufficiency in growth signals, and evading apoptosis, indicating their potential roles in tumorigenesis." (PMID 35741849, 2022). "However, the expression analysis showed high overexpression of PRLR and GHRHR, both of these receptors representing known targets for chemotherapy in cancer." (PMID 35978432, 2022). "Initially we evaluated whether EGF induces PRLR gene expression and transcription in MCF-7 cancer cells." (PMID 27564112, 2016). "Out of the models containing “hormone blood level” and “tissue group” a relationship was only found for PRLR mRNA expression: PRL blood levels had a negative relationship with PRLR gene expression only in malignant neoplasms (p = 0.025)." (PMID 26370564, 2015).
cancer (continued). "The optical density measurements from immunoblots demonstrated higher PRLR expression in cancer cell lines in comparison with the non-tumorigenic HaCaT cell line." (PMID 24148306, 2013). "However, despite its potential antagonistic properties against PRLR, LFA102 has not shown persuasive benefits in clinical trials, indicating a single-targeted approach to PRLR is insufficient to suppress clinical cancer progression." (PMID 38898487, 2024). "Moreover, whilst Prl elicits JAK2-STAT5 signalling and ERK signalling in cancer cells, normal MECs do not produce an ERK response, suggesting that important differences in the regulatory mechanisms controlling PrlR signalling exist in different contexts." (PMID 28676702, 2017). "Malignant tumors with invasive growth of FFPE samples showed significantly lower gene expression of hormone receptors than tumors that were not invasive (ESR1 p = 0.014; PGR p = 0.033; PRLR p = 0.0006; GHR p = 0.011, respectively)." (PMID 27649560, 2016).